SNORA63E (small nucleolar RNA, H/ACA box 63E)
Gene: Small nucleolar RNA gene on chromosome 3 (183,453,814 to 183,453,944, forward strand). Ensembl gene ENSG00000199363.
Gene Ontology:
Biological process: RNA processing
Cellular component: nucleolus
Homologues: Orthologues: chimpanzee SNORA63 (99% identical), macaque SNORA63 (97% identical), dog SNORA63 (89% identical), pig SNORA63 (88% identical), guinea pig SNORA63E (85% identical), mouse Gm25852 (80% identical). Paralogues in human: SNORA63 (78% identical), SNORA63 (77% identical), SNORA63C (77% identical), SNORA63D (76% identical), SNORA63B (63% identical), SNORA63 (60% identical), SNORA63 (59% identical), SNORA63 (56% identical), SNORA63 (41% identical).